KCNA2 (potassium voltage-gated channel subfamily A member 2)
Diseases named in the same sentence as KCNA2 in open-access papers (continued):
Sharing a sentence is not in itself a finding about the gene and the disease.
Ataxia (16 papers, 2015 to 2025). Ataxia refers to impaired coordination of voluntary muscle movement. "In future work, we will examine the efficacy of the extracts and their constituents in counteracting the effects of ataxia-linked KCNA2 variants." (PMID 37280215, 2023). "Patients harboring either a gain-of-function mutation or a combination of gain- and loss-of-function mutations in KCNA2 are more likely to develop ataxia and cerebellar atrophy." (PMID 37374132, 2023). "Acetazolamide successfully remits ataxia and myoclonic epilepsy caused by KCNA2 variants in some patients." (PMID 34576077, 2021). "Here we describe a novel de novo variant in KCNA2, E236K, identified in a Serbian proband affected by non-progressive ataxia, moderate intellectual disability and generalized epilepsy." (PMID 34576077, 2021).
Encephalopathy (11 papers, 2018 to 2025). Encephalopathy is a term that means brain disease, damage, or malfunction. "The patient expanded the mutational spectrum of KCNA2-related encephalopathy and provided new insight into the complex genetic disorder." (PMID 32903602, 2020). "Our findings highlighted the two mosaic mutations responsible for the pathogenesis of KCNA2-related encephalopathy." (PMID 32903602, 2020). "Interestingly, both gain- and loss-of-function mutations of KCNA2 are associated with encephalopathy." (PMID 37374132, 2023). "Recently, studies have shown that blocking Kv1.2 currents with 4-aminopyridine (4-AP), a small organic compound, can mitigate the gain-of-function defects in patients with KCNA2-related encephalopathy." (PMID 40559857, 2025). "4-aminopridine has been shown to improve symptoms in patients with gain-of-function KCNA2 encephalopathy." (PMID 37374132, 2023). "Blocking of Kv1.2 with 4-aminopyridine (a small organic compound) was shown to antagonize gain-of-function defects in KCNA2-encephalopathy patients." (PMID 37624263, 2023). "The cognitive impairment could be due to an encephalopathy involving functionally disturbed brain function due to interfering synaptic protein autoantibodies such as CASPR2, KCNA2 or glycin autoantibodies in strategically cognition-relevant structures like the hippocampus." (PMID 33677623, 2021). "Another individual, with KCNA2-DEE (gain-of-function phenotype), who had encephalopathy (background slowing, no epileptiform activity, rare clinical seizures) and mild ID, exhibited a progressive decline in cognition and mobility." (PMID 39882024, 2025).
peripheral nerve injury (10 papers, 2014 to 2024). Injury to a peripheral nerve. "Dnmt3a, an epigenetic repressor, participates in epigenetic silencing of several genes (such as Oprk1 and Kcna2 besides Oprm1) in the injured DRG following peripheral nerve injury." (PMID 29170626, 2017). "Potassium voltage-gated channel subfamily A member 2 (KCNA2) is a major potassium channel subunit, and its expression is regulated by overlapping antisense RNA when facing peripheral nerve injury or neuralgia." (PMID 30323747, 2018). "DNMT1, with an established role in canonical methylation activity but also with recognized de novo methylation actions, and DNMT3a, through repression of Kcna2, were found upregulated in the DRG after peripheral nerve injury in mice, and their inhibition or knockout diminished pain hypersensitivity." (PMID 37108466, 2023).
channelopathies (8 papers, 2018 to 2025). "Furthermore, both the gain- and loss-of-function phenotype can be observed in other channelopathies such as KCNA2, GRIN1, and DEAF1 gene mutations." (PMID 29545233, 2018). "Subsequently, several other GOF mutations in the KCNA2 gene, such as E157K, H310Y, H310R, and E236K, were identified and proven as major contributors to Kv1.2-related channelopathies." (PMID 40559857, 2025). "Previous studies have shown that the biophysical properties of channelopathy-causing variants, such as SCN1A, KCNA2, KCNQ2, and GluN2B may correlate with phenotypes." (PMID 35845605, 2022).
Cognitive impairment (6 papers, 2020 to 2025). Abnormal cognition is characterized by deficits in thinking, reasoning, or remembering. "The pathogenetic role of KCNA2 antibodies in cognitive impairment is not well delineated; clinical presentations are heterogeneous, and thus a causal link between antibodies remains questionable." (PMID 33445475, 2021).
developmental and epileptic encephalopathy (5 papers, 2021 to 2026). An epilepsy associated with developmental impairment that may be due to either the underlying etiology or the superimposed epileptic activity, or both. "Either gain- or loss-of-function KCNA2 variants can cause severe neurological disease, assigned developmental epileptic encephalopathy (DEE) type 32." (PMID 41914769, 2026). "The first variant, rs786205232 (1:110603893C > T), is a missense variant in the KCNA2 gene responsible for developmental and epileptic encephalopathy 32 (MIM 616366)." (PMID 39498263, 2024).
developmental delay (4 papers, 2020 to 2026). "We characterized two KCNA2 variants from patients with global developmental delay." (PMID 41914769, 2026).
early-onset epileptic encephalopathy (4 papers, 2020 to 2025). "Variants affecting prolines in the PVP motif and in closely related residues have been identified in KCNA2- and recently in KCNA1-associated early-onset epileptic encephalopathy." (PMID 33802230, 2021).
myoclonic epilepsy (4 papers, 2015 to 2023). A group of epilepsy syndromes in which myoclonic seizures are a prominent feature. "This evidence suggests that performing genomic testing including the KCNA2 gene in preschool patients affected by myoclonic epilepsy, especially when associated with delayed neurodevelopment." (PMID 35178022, 2022). "This is the first case of myoclonic epilepsy in a toddler due to a c.889C>T KCNA2 missense variant." (PMID 35178022, 2022). "According to the literature, this case supports the correlation between myoclonic epilepsy and KCNA2 alterations." (PMID 35178022, 2022).
temporal lobe epilepsy (3 papers, 2024 to 2025). A localization-related (focal) form of epilepsy characterized by recurrent seizures that arise from foci within the temporal lobe, most commonly from its mesial aspect. "Limited to patients with temporal lobe epilepsy, we detected a significant correlation between the exponent and the cortical expression of GABRA1, GRIN2A, GABRD, GABRG2, KCNA2 and PDYN genes." (PMID 39056027, 2024).
dementia (2 papers, 2021 to 2022). Loss of intellectual abilities interfering with an individual's social and occupational functions. "In another recent study on patients with dementia, we identified CASPR2, KCNA2 autoantibodies in blood samples." (PMID 34393763, 2021).
diabetic neuropathy (2 papers, 2020 to 2022). A chronic, pathological complication associated with diabetes mellitus, where nerve damages are incurred due to diabetic microvascular injury involving small blood vessels that supply these nerves, resulting in peripheral and/or autonomic nerve dysfunction. "Five of them, KCNA2, KCNA4, KCNQ5, KCNN1 and KCNS1, were also negative for screening in a diabetic neuropathy population." (PMID 36430572, 2022).
generalized epilepsy (2 papers, 2018 to 2021). Epilepsy that is characterized by generalized seizure types and may have typical interictal and/or ictal EEG findings that accompany generalized seizure types (for example generalized spike-wave). "Then, we analyzed the SNP distributions of generalized epilepsy (GE) patients, which showed that the rs3887820 SNP of the KCNA2 gene was associated with susceptibility to GE." (PMID 30441785, 2018).
Obesity (2 papers, 2021 to 2026). Accumulation of substantial excess body fat. "Here, using next-generation sequencing, we identified pathogenic KCNA2 variants in patients of diverse ancestry with DCM, Obesity, and Sleep Apnea (termed DOSA)." (PMID 41735622, 2026).
osteoarthritis (2 papers, 2021). A noninflammatory degenerative joint disease occurring chiefly in older persons, characterized by degeneration of the articular cartilage, hypertrophy of bone at the margins and changes in the synovial membrane. "In addition, Kcna2 expression is associated with hyperalgesia of osteoarthritis pain." (PMID 34632937, 2021).
Seizure (2 papers, 2007 to 2018). A seizure is an intermittent abnormality of nervous system physiology characterized by a transient occurrence of signs and/or symptoms due to abnormal excessive or synchronous neuronal activity in the brain. "It was found that the rs3887820 SNP in the KCNA2 gene was associated with generalized myoclonic seizure." (PMID 30441785, 2018). "This study suggests that a significant association exists between the KCNA2 SNP rs3887820 and increased susceptibility to generalized myoclonic seizure." (PMID 30441785, 2018).
skin cutaneous melanoma (2 papers, 2023 to 2025). "While other potassium voltage-gated genes such as KCNA2, KCNA3, and KCNA5 have been investigated across various cancers—including skin melanoma, uterine corpus endometrial carcinoma, gastric adenocarcinoma, LUAD, and LUSC in-depth studies of KCNA7’s expression in cancer remain lacking." (PMID 40568194, 2025).
Generalized myoclonic seizure (1 paper, 2018). A generalized myoclonic seizure is a type of generalized motor seizure characterized by bilateral, sudden, brief (<100 ms) involuntary single or multiple contraction of muscles or muscle groups of variable topography (axial, proximal limb, distal). "Only one SNP in KCNA2, rs3887820, showed significant association with increased risk of susceptibility to generalized myoclonic seizure (p-value < 0.001)." (PMID 30441785, 2018).
heart failure (1 paper, 2023). Inability of the heart to pump blood at an adequate rate to meet tissue metabolic requirements. "For example, antisense lncRNA Kcna2 (Long non-coding RNA Potassium Voltage-Gated Channel Subfamily A Member 2) is linked to a higher prevalence of ventricular arrhythmias, which are irregular heartbeats that only impact the heart’s lower chambers in heart failure patients." (PMID 38250803, 2023). "The study found that Kcna2 knockdown in the heart decreased the slow component of the rectifier potassium current (IKs) and prolonged action potentials in cardiomyocytes, consistent with the changes observed in heart failure." (PMID 38250803, 2023).
hereditary spastic paraplegia (1 paper, 2021). Hereditary spastic paraplegias (HSP) comprise a genetically and clinically heterogeneous group of neurodegenerative disorders characterized by progressive spasticity and hyperreflexia of the lower limbs. "The recurrent KCNA2 variant c.881G > A, leading to an amino-acid exchange at position 294 within the voltage sensing domain, was identified in individuals with hereditary spastic paraplegia (HSP) as an additional phenotype." (PMID 33802230, 2021).
Moyamoya disease (1 paper, 2025). Moyamoya disease (MMD) is a rare intracranial arteriopathy involving progressive stenosis of the cerebral vasculature located at the base of the brain causing transient ischemic attacks or strokes. "RGS1, MUC1, KCNA2, TAC1, and SOST were all found to be up-regulated in moyamoya disease." (PMID 40462179, 2025).
tonic-clonic seizures (1 paper, 2015). "A 788 kb microdeletion involving the Shaker-like voltage-gated potassium channel gene KCNA2 (1p13, chr1: 111,136,002–111,174,096, hg19) was identified in a male GGE patient with generalised tonic-clonic seizures starting at the age of 14." (PMID 25950944, 2015).
Ventricular arrhythmia (1 paper, 2023). "Conversely, Kcna2 overexpression in the heart significantly attenuated the CHF-induced decreases in the IKs, AP prolongation, and ventricular arrhythmias." (PMID 38250803, 2023).
cancer (8 papers, 2019 to 2025). A tumor composed of atypical neoplastic, often pleomorphic cells that invade other tissues. "Overall, these data highlighted SKCM, UCEC, STAD, LUSC, and LUAD to be the five cancers with the highest KCNAs mutation frequency and revealed KCNA2, KCNA3, and KCNA5 to be the most expressed KCNA family genes in these tumours." (PMID 36978819, 2023). "We evaluated the overall genetic alterations in all KCNA genes (KCNA1, KCNA2, KCNA3, KCNA4, KCNA5, KCNA6, KCNA7, KCNA10) using the TCGA Pan-Cancer Atlas dataset, collecting data from 32 human cancers (10,953 patients in total)." (PMID 36978819, 2023). "To explore the prognostic significance of KCNA2, KCNA3, and KCNA5 expression in cancer patients, we took advantage of the Kaplan–Meier analysis by sorting samples for high and low KCNAs expression according to the quartile KCNAs mRNA level." (PMID 36978819, 2023). "The results also revealed a decrease in KCNA2, SNCG, and TGFB2 levels with a simultaneous increase in GNB1, CXCL12, SNCA, and OPRK1 expression in G2 cancer compared to control." (PMID 34768458, 2021). "The KCNA2 mRNA level does not significantly differ in controls compared to tumoral samples in any of the considered cancer types." (PMID 36978819, 2023). "Among those genes, we focused on KCNA2, TNFRSF13B and ADAM6, which exhibit a 11x, 7x and 3.5x fold increase respectively, since they were among the 9 differential expressed genes with p values <0.00001 that have a clearer biological role in cancer." (PMID 35990685, 2022). "Contrary to KCNA3 and KCNA5, KCNA2 has no prognostic value for any of the considered cancers." (PMID 36978819, 2023).
neurological disorders (6 papers, 2021 to 2026). "Pathogenic variants in KCNA2, encoding for the voltage-gated potassium channel Kv1.2, have been identified as the cause for an evolving spectrum of neurological disorders." (PMID 33802230, 2021). "A spectrum of neurological disorders may be caused by mutations in the KCNA2 gene, which encodes voltage-gated potassium channel Kv1.2." (PMID 37008993, 2023).
tumor (3 papers, 2018 to 2024). "With KCNA2, KCNA3, and KCNA5 being the most abundant transcripts of the Shaker gene family in SKCM, UCEC, STAD, LUSC, and LUAD, we compared their expression levels in both tumour and normal samples." (PMID 36978819, 2023).
genetic disorder (2 papers, 2020 to 2021). "In some genetic disorders, especially KCNQ2 and KCNA2, there was always the first stage of different EEG patterns preceding ESES." (PMID 33897753, 2021).
movement disorder (2 papers, 2025). Neurological conditions resulting in abnormal voluntary or involuntary movement, which may impact the speed, fluency, quality and ease of movement. "Myoclonus is the main type of movement disorder associated with CACNA1A (approximately 82.8%), KCNA2 (75%), SCN1A (approximately 61.5%), and SCN8A (60%) mutations." (PMID 40217411, 2025).
neurodevelopmental disorder (2 papers, 2020 to 2024). A behavioral and cognitive disorder with onset during the developmental period that involves impaired or aberrant development of intellectual, motor, or social functions. "KCNA2 mutations are implicated in human neurodevelopmental disorders through two different mechanisms: predicting either hyperexcitability or electrical silencing of KV1.2-expressing neurons." (PMID 39434833, 2024).
KCNA2 also shares sentences with these, for which no sentence is quoted: episodic ataxia (6 papers); episodic ataxia type 1 (3); Intellectual disability (3); neuropathic pain (3); amyotrophic lateral sclerosis (2); autism spectrum disorder (2); breast cancer (2); diabetes (2); Dravet syndrome (2); epilepsy syndrome (2); infantile epileptic encephalopathy (2); injury (2); Morvan syndrome (2); neuropathy (2); Parkinson disease (2); progressive myoclonus epilepsy (2); Spastic paraplegia (2); type 2 diabetes (2); uterine corpus endometrial carcinoma (2); Alzheimer disease (1); Angelman syndrome (1); Aphasia (1); Arrhythmia (1); atrial fibrillation (1); autism (1); Autoimmunity (1); Benign familial neonatal seizures (1); biotinidase deficiency (1); bipolar disorder (1); bone cancer (1).
A further 40 diseases each share a sentence with KCNA2 in 1 paper.